SCN8A (sodium voltage-gated channel alpha subunit 8)
Description:
Pore-forming subunit of a voltage-gated sodium channel complex assuming opened or closed conformations in response to the voltage difference across membranes and through which sodium ions selectively pass along their electrochemical gradient. Contributes to neuronal excitability by regulating action potential threshold and propagation. [Isoform 5]: More specifically expressed in non-neuronal cells, could play a role in sodium release from intracellular compartments and participate in the control of podosomes formation and macrophages adhesion and movement.
Synonyms: MED; Nav1.6; NaCh6; PN4; CerIII; CIAT; BFIS5; DEE13; EIEE13; MYOCL2
Tractability: Small molecule: an approved drug acts on it; a structure with a bound ligand is known; a high-quality ligand is known; it belongs to a druggable protein family. Antibody: UniProt places it where antibodies can reach, with high confidence; its Gene Ontology location is reachable by antibodies, with high confidence; UniProt predicts a signal peptide or a membrane-spanning region. PROTAC: UniProt records ubiquitination sites on it; a small molecule that binds it is known.
Target class: Voltage-gated ion channel; Voltage-gated sodium channel; Ion channel
Gene: Protein-coding gene on chromosome 12 (51,590,266 to 51,812,864, forward strand). Ensembl gene ENSG00000196876.
Subcellular location: Cell membrane; Cell projection, axon; Cytoplasmic vesicle (Isoform 5); Cell projection, podosome
Subcellular location (Human Protein Atlas): Plasma membrane; Cell Junctions; Vesicles
Pathways (Reactome):
Developmental Biology: Interaction between L1 and Ankyrins
Muscle contraction: Phase 0 - rapid depolarisation
Gene Ontology:
Molecular function: protein binding; sodium ion binding; voltage-gated sodium channel activity; monoatomic cation channel activity; monoatomic ion channel activity
Biological process: action potential; membrane depolarization during action potential; cardiac muscle cell action potential involved in contraction; myelination; peripheral nervous system development; sodium ion transmembrane transport; sodium ion transport; monoatomic ion transport; transmembrane transport
Cellular component: cytoplasmic vesicle; plasma membrane; voltage-gated sodium channel complex; axon; axon initial segment; membrane; node of Ranvier; Z disc; podosome
Genetic constraint (gnomAD): Loss-of-function variants: 21 observed, 160.18 expected, observed/expected ratio (o/e) 0.13, 90% interval 0.092 to 0.19. The upper end of that interval is the gene's LOEUF score, 0.19, which puts it in group 1 of 6, group 1 being the genes least tolerant of losing a copy. Missense variants: 1,010 observed, 2,416.9 expected, observed/expected ratio (o/e) 0.42, 90% interval 0.4 to 0.44. Synonymous variants: 811 observed, 889.19 expected, observed/expected ratio (o/e) 0.91, 90% interval 0.86 to 0.97.
Gene-disease validity (ClinGen):
ClinGen rates the evidence that SCN8A causes each of these diseases.
complex neurodevelopmental disorder (autosomal dominant): Definitive. A disorder that involves more than one phenotype associated with the central nervous system, including but not limited to intellectual disability, autism, and seizures (epilepsy).
Homologues: Orthologues: chimpanzee SCN8A (99% identical), macaque SCN8A (99% identical), pig SCN8A (99% identical), dog SCN8A (99% identical), rabbit SCN8A (99% identical), rat Scn8a (99% identical), mouse Scn8a (99% identical), guinea pig SCN8A (91% identical), zebrafish scn8ab (84% identical), zebrafish scn8aa (82% identical), tropical clawed frog scn8a (82% identical). Paralogues in human: SCN2A (77% identical), SCN1A (77% identical), SCN3A (75% identical), SCN9A (71% identical), SCN5A (64% identical), SCN4A (63% identical), SCN10A (56% identical), SCN11A (47% identical), SCN7A (44% identical), CACNA1A (25% identical), CACNA1B (24% identical), CACNA1C (24% identical), and 14 more.
Diseases named in the same sentence as SCN8A in open-access papers:
SCN8A is named in the same sentence as 150 diseases in open-access papers, as found by Europe PMC text mining. Sharing a sentence is not in itself a finding about the gene and the disease. The quoted sentences say what the papers report.
epilepsy (164 papers, 2011 to 2026). A brain disorder characterized by episodes of abnormally increased neuronal discharge resulting in transient episodes of sensory or motor neurological dysfunction, or psychic dysfunction. "SCN8A expression increases following birth and maintains expression in multiple brain regions commonly associated with epilepsy, such as the hippocampus, cortex, and thalamus." (PMID 40830973, 2025). "Despite significant scientific progress since the 2012 discovery that variants in the SCN8A gene can cause human epilepsy, disease mechanisms and best practices for management of SCN8A-related disorders (SCN8A-RD) remain incompletely understood." (PMID 40830973, 2025). "There are known to be over 700 cases worldwide with pathogenic variants in SCN8A, accounting for ~ 1% of all cases of epilepsy with encephalopathy." (PMID 40830973, 2025). "More than 150 mutations in the SCN8A gene have been identified to be potentially associated with epilepsy." (PMID 40565516, 2025). "SCN8A-related epilepsy is associated with a progressive clinical course and structural changes in the brain." (PMID 41573391, 2025). "Pathogenic mutations in the SCN8A gene are linked to various epilepsy phenotypes, spanning from benign familial infantile seizures (BFIS) in select families to severe developmental and epileptic encephalopathies (DEEs) that manifest early in life." (PMID 38846250, 2024). "These comparisons highlight the variability in clinical presentations, epilepsy diagnoses, and genetic diagnoses among the patients with SCN8A pathogenic variations." (PMID 38233770, 2024). "Sodium channel 8 alpha (SCN8A) mutations encompass a spectrum of epilepsy phenotypes with diverse clinical manifestations, posing diagnostic challenges." (PMID 38846250, 2024). "Common biophysical effects of SCN8A epilepsy mutations include greater levels of persistent and/or resurgent sodium currents." (PMID 38895634, 2024). "CBD also increased resistance to induced seizures in a mouse model of epilepsy associated with a mutation in the Scn8A gene, encoding Nav1.6, a subtype of Navs." (PMID 38257386, 2024). "Missense mutations in SCN8A, constituting approximately 1% of cases of epileptic encephalopathy (EE), are linked to a diverse range of epilepsy phenotypes." (PMID 38846250, 2024). "Through a collaborative network of caregivers and clinicians, we collected data about epilepsy, cognitive/motor abilities, medications, and relevant comorbidities of patients harboring a pathogenic SCN8A variant." (PMID 39361253, 2024). "SCN8A developmental and epileptic encephalopathy (DEE) is a severe epilepsy syndrome resulting from mutations in the voltage-gated sodium channel Nav1.6, encoded by the gene SCN8A." (PMID 39435659, 2024). "The functional consequences of epilepsy-associated pathogenic variants in the voltage-gated sodium channel Nav1.6-encoding gene SCN8A are affected by splice isoform and molecular context." (PMID 38771640, 2024). "In a recent case report, fenfluramine was found to decrease seizure frequency by 60%–90% in three patients with SCN8A-associated epilepsy." (PMID 38895634, 2024). "SCN8A variants in patients with epilepsy primarily result in GoF in Nav1.6 and hyperexcitability of neurons in the central nervous system." (PMID 38233770, 2024). "The first SCN8A-associated epilepsy mutation was identified in 2012, and since then, over 250 SCN8A mutations have been reported." (PMID 38895634, 2024). "Subsequently, SCN8A variants were discovered in individuals affected with epilepsy having a wider spectrum of clinical severity as well as NDD without seizures." (PMID 38771640, 2024). "We also evaluated the effects of fenfluramine administration, which was recently associated with a 60%–90% decrease in seizure frequency in three patients with SCN8A-associated epilepsy." (PMID 38895634, 2024).
epilepsy (continued). "A recent study also reported a significant reduction in seizure frequency in three patients with SCN8A epilepsy mutations who were treated with fenfluramine." (PMID 38895634, 2024). "Long-term management and monitoring are essential in optimizing outcomes for patients with SCN8A mutations and refractory epilepsy." (PMID 38846250, 2024). "In a mouse model of Scn8a-associated epilepsy (encoding Nav1.6), CBD has shown efficacyin reducing seizures frequency at a dose of 320–360 mg/kg." (PMID 37050032, 2023). "In our study, there were nine SCN8A variant-related epilepsy patients, of whom eight showed moderately severe mental and motor impairment." (PMID 38174099, 2023). "Mutations in VGSCs (such as in SCN1A, SCN2A, SCN3A, and SCN8A) can lead to defects in inactivation gating, enhancing persistent sodium currents (INaP) and firing of neurons, resulting in epilepsy and ataxia." (PMID 40217485, 2023). "We previously demonstrated that reducing Scn8a expression is therapeutic in Scn1a+/− mice and in mice with epilepsy caused by loss of the potassium channel genes Kcna1 and Kcnq2." (PMID 37901435, 2023). "Of relevance then, gain-of-function mutations in the Scn8a gene, which encodes the Nav1.6 channel isoform, lead to the development of epilepsy and intellectual disabilities." (PMID 38115011, 2023). "SCN1A/SCN2A/SCN8A variant-related epilepsy was generally manifested at an earlier age, while the SCN3A/SCN9A/SCN1B variant-related subtype showed a later age at onset." (PMID 38174099, 2023). "This case shows that sodium channel blockers such as CBZ, OXC, and LCS are highly or partially effective in SCN8A variant-related epilepsy." (PMID 38174099, 2023). "Upregulation of Nav1.6 in the AIS is shown to result in an upsurge in spontaneous and repetitive firing of cortical neurons, a plausible explanation for why SCN8A mutations in patients with epilepsy are mainly gain-of-function and impact the AP threshold." (PMID 40217485, 2023). "SCN8A, which encodes a voltage-gated sodium channel, is an established epileptic encephalopathy gene and is associated here with common epilepsies." (PMID 37653029, 2023). "In the current manuscript, we provide the first evaluation of CBD in a mouse model of Scn8a-associated epilepsy." (PMID 35153788, 2022). "Epilepsy-associated SCN8A channelopathies are largely heterogeneous in their pathogenicity, phenotypes, and responses to treatment." (PMID 35805192, 2022). "This study investigated several genetic variants of SCN genes (SCN1A, SCN2A, SCN3A, SCN1B, SCN2B, SCN3B and SCN8A) and their association with epilepsy risk; these genes have been studied in this regard and conflicted results were reported." (PMID 35801810, 2022). "This is the first documented report of a stereoelectroencephalography (SEEG) evaluation and resective surgery outcome in an adult patient with epilepsy related to SCN8A mutation." (PMID 35492509, 2022). "In this regard, the concentration of vitamin B12 found to be associated with the rs303778 of SCN8A in epilepsy patients in this study." (PMID 35801810, 2022). "More than 150 distinct epilepsy-related mutations have been identified in the SCN8A gene that encodes Nav1.6." (PMID 35805192, 2022). "Prior to the development of the mouse lines expressing human SCN8A epilepsy mutations, most of the published Scn8a mouse models carried loss-of-function missense or truncating Scn8a mutations." (PMID 34867351, 2021). "In particular, Kcnq5 and Scn8a are both expressed only in cPNs and implicated in epilepsy and/or hyperactivity." (PMID 34188164, 2021). "Pathogenic variants in SCN8A have been associated with a wide spectrum of epilepsy phenotypes, ranging from benign familial infantile seizures to epileptic encephalopathies with variable severity." (PMID 33789662, 2021). "GOF variants of SCN8A‐encoding Nav1.6 potentially leads to sudden unexpected death in epilepsy (SUDEP) due to arrhythmia of the brain and the heart." (PMID 34709746, 2021).
epilepsy (continued). "Accordingly, most patients with SCN8A mutations develop epilepsy in infancy (median age = 4 months)." (PMID 34842787, 2021). "Mutations affecting three alpha subunit genes (SCN1A, SCN2A, and SCN8A) have been shown to cause epilepsies of variable severity." (PMID 34842787, 2021). "Initial genetic studies using rodents revealed that the SCN8A gene is also mutated in epilepsy with absence seizures, a genetic generalized epilepsy (GGE)." (PMID 33841294, 2021). "This Scn8a mouse model harbors the germline knock-in mutation N1768D (D/+), a mutation identified in an SCN8A epilepsy patient that died of SUDEP." (PMID 33762902, 2021). "Inherited mutations almost exclusively yield benign infantile epilepsies; however SCN8A-related EE/DEE due to parental germline mosaicism has been described." (PMID 34842787, 2021). "Recently, using CRISPR/Cas9 technology, we generated a mouse line expressing the SCN8A R1620L mutation, which was identified in a patient with relatively mild epilepsy and behavioral deficits." (PMID 34867351, 2021). "Heterozygous missense mutations of SCN8A have recently been associated with a wide spectrum of epilepsies." (PMID 34842787, 2021). "Over 150 distinct mutations in the SCN8A gene have since been identified in patients with epilepsy and account for up to 1% of epilepsies." (PMID 34202119, 2021). "Sodium channel blockers have been avoided in SCN1A-related cases (loss-of-function variants) but preferred in early-onset SCN2A and SCN8A epilepsy (gain-of-function variants)." (PMID 33726816, 2021). "Unfortunately, a disproportionate number of SCN8A-associated epilepsies remain refractory to antiepileptic treatments." (PMID 34202119, 2021). "To date, most identified human SCN8A-epilepsy associated mutations have been de novo amino acid substitutions, many of which are predicted or shown to have gain-of-function properties." (PMID 34867351, 2021). "The understanding of the role of SCN8A in seizure initiation and epilepsy became well-known following the detection of de novo mutations in patients having epileptic encephalopathies with varying seizure severities." (PMID 33841294, 2021). "These works enhanced the understanding of the gain-of-function roles of SCN8A mutations in epileptic encephalopathies, and more importantly, that SCN8A is a causative gene in children epilepsies." (PMID 33841294, 2021). "Genetic variants in the voltage-gated sodium channels SCN1A, SCN2A, SCN3A, and SCN8A are leading causes of epilepsy, developmental delay, and autism spectrum disorder." (PMID 34425903, 2021). "Most recently, few cases of SCN8A-related epilepsies with “milder” phenotype were associated with benign familial infantile seizures-5 (BFIS5; OMIM #617080)." (PMID 33013363, 2020). "Sudden unexpected death in epilepsy (SUDEP) has also been linked to SCN8A mutations, described as the most common cause of death in epilepsy patients." (PMID 33013363, 2020). "Reports have suggested that patients with SCN8A-related epilepsy have increased risk of SUDEP, ranging from 1% to 10%." (PMID 33013363, 2020). "In a meta analysis of epilepsy genetics research over the past decade, from 5185 papers published from 2009 to 2018, 4% of the “occurrences” related with epilepsy corresponded to SCN8A mutations." (PMID 31841065, 2020). "Overexpression of Nav1.6 in the AIS has been shown to cause an increase in spontaneous and repetitive firing, a possible explanation for why SCN8A mutations in epilepsy patients are predominantly GoF and affect the action potential threshold." (PMID 33013363, 2020).
epilepsy (continued). "SCN8A, which encodes the NaV1.6 α-subunit is also related to epilepsy and approximately 100 mutations have been reported in patients with severe Early Infantile Epileptic Encephalopathy subtype 13 (EIEE13)." (PMID 32134913, 2020). "The first human epilepsy mutation in SCN8A was identified in 201230, and since then, there have been a number of additional SCN8A mutations reported." (PMID 29317669, 2018). "Through the work of the EGI, we report here the identification of three novel disease-causing variants in alternative exon 5 A of SCN8A in three unrelated patients with epilepsy." (PMID 29121005, 2018). "The second case involved a 9-year old female with a de novo SCN8A missense mutation (c.5615G>A; p.Arg1872Gln) that presented with early onset drug-resistant epilepsy." (PMID 29184379, 2017). "Targeted array analysis of epilepsy genes showed a de novo heterozygous SCN8A mutation, c.5610A>T p.Glu1870Asp, which was predicted to be possibly damaging." (PMID 26252990, 2016). "By targeted array analysis of epilepsy genes, a de novo heterozygous mutation in SCN8A, c.4787C>G (p.Ser1596Cys) was detected." (PMID 26252990, 2016). "De novo mutations in SCN8A have been discovered through genome and exome sequencing, and SCN8A can now be evaluated with commercial epilepsy panels." (PMID 27900360, 2016). "Several studies have associated mutations in SCN8A with epilepsy, intellectual disability, and cranial features such as microcephaly." (PMID 27900360, 2016). "Herein, we describe 4 patients with a missense SCN8A mutation and epilepsy who all show a remarkably good response on high doses of phenytoin and loss of seizure control when phenytoin medication was reduced, while side effects were relatively mild." (PMID 26252990, 2016). "In a screen for de novo mutations in 264 patients with infantile spasms or Lennox-Gastaut syndrome, the SCN8A mutation p.Leu876Gln was found in a child with Lennox-Gastaut (Epi4K Consortium and Epilepsy Phenome/Genome Project, 2013)." (PMID 24194747, 2013). "In the mature brain, SCN8A (Nav1.6) gain-of-function mutations cause hyperexcitability in pyramidal neurons, resulting in epilepsy, while LOF mutations suppress neuronal excitability and are implicated in intellectual disabilities, cognitive deficits, and motor impairment." (PMID 41010287, 2025). "Similarly, SCN8A-related epilepsy exhibits a range of phenotypes, with LGS associated with GOF variants, though epilepsy onset is typically later in infancy compared to SCN2A." (PMID 40310132, 2025). "For individuals with DEEs related to GOF variants in SCN2A and SCN8A, sodium channel blockers may be beneficial in the management of epilepsy; in contrast, with LOF variants in SCN2A and SCN8A, sodium channel blockers may worsen the epilepsy phenotype." (PMID 38540325, 2024). "The results of this study and previous evidence for the role of noradrenergic modulation in SCN8A-associated epilepsy, provide support for the continued investigation of the potential of CVD and other β-adrenergic receptor blockers as treatments for SCN8A-associated epilepsy." (PMID 38895634, 2024). "Finally, we illustrate the importance of controlling for splice isoform by the functional study of an epilepsy-associated SCN8A haplotype with 2 de novo missense variants of uncertain significance within or outside exon 5N." (PMID 38771640, 2024). "In addition, the serotonergic drug fenfluramine is gaining interest as a possible treatment for SCN8A-associated epilepsy." (PMID 38895634, 2024). "Based on its mechanism of action, we speculate that cenobamate might also be beneficial in SCN8A-associated epilepsy." (PMID 38895634, 2024).